MSLN (mesothelin)
Diseases named in the same sentence as MSLN in open-access papers (continued):
Sharing a sentence is not in itself a finding about the gene and the disease.
pancreatic cancer (continued). "N-ERC/mesothelin was detected in the supernatants of cultured human pancreas cancer cells and correlated with the expression levels of ERC/mesothelin." (PMID 25347530, 2014). "In the present study, in agreement with our previous report, the serum level of N-ERC/mesothelin correlated with pancreas tumor size in rats." (PMID 25347530, 2014). "MSLN-overexpressing pancreatic cancer cell lines showed increased cyclin E and cyclin dependent kinase 2 expression, resulting in increased cell proliferation and cell cycle progression." (PMID 25506917, 2014). "An anti-MSLN CD4+ T cell response was observed in 84% of pancreatic cancer patients (21 out of 25), 66.7% of patients with benign disease (10 out of 15) and 43.7% of healthy donors (7 out of 15)." (PMID 24520352, 2014). "Using a monoclonal antibody (5B2) directed against MSLN, expression was identified in 91–100% of pancreatic cancer tissue." (PMID 24520352, 2014). "Here, we demonstrate that the plasma levels of Mesothelin and IL-10 are significantly increased in patients with pancreatic carcinoma." (PMID 24520352, 2014). "For example, mesothelin is a commonly overexpressed protein on many human cancer cells, including ovarian and pancreatic cancer." (PMID 24354786, 2013). "The humoral immune response to mesothelin has been found to be a favorable prognostic factor for pancreatic cancer." (PMID 23509731, 2013). "Mesothelin (MSLN), is a membrane glycoprotein normally expressed on mesothelial cells, but is over-expressed in most pancreatic cancers." (PMID 23874581, 2013). "Our previous study has shown that mesothelin (MSLN) is a potential immunotherapeutic target for pancreatic cancer." (PMID 23874581, 2013). "MORAb-009, a monoclonal antibody against mesothelin, is being tested in a phase I trial of 11 patients (three with pancreatic cancer)." (PMID 23509731, 2013). "Mesothelin levels were detected by western blot and RT-PCR assay in human pancreatic cancer AsPC-1, HPAC and Capan-2, Capan-1 and MIA PaCa-2 cell lines." (PMID 23034174, 2012). "One example is mesothelin – a protein also commonly overexpressed on many human cancer cells, including ovarian and pancreatic cancer." (PMID 22509395, 2012). "In the present study, we have shown that mesothelin was overexpressed in the human pancreatic cancer cell lines." (PMID 23034174, 2012). "The significant reduction in pancreatic cancer growth by mesothelin shRNA indicated the importance of shRNA blockage and opened a door for shRNA pancreatic cancer therapy that targets MSLN." (PMID 23034174, 2012). "Silencing of mesothelin expression significantly decreased cell proliferation and promoted apoptosis in pancreatic cancer cells in vitro and inhibited tumor growth in vivo." (PMID 23034174, 2012). "The reason for choosing these pancreatic cancer cell lines was due to the fact that these cell lines showed much higher expression of mesothelin." (PMID 23034174, 2012). "Otherwise,knockdown of mesothelin sensitized pancreatic cancer cells to radiation and TNF-a-induced apoptosis." (PMID 23034174, 2012). "Our previous data showed that MSLN-induced Stat3/cyclin E promotes survival/proliferation of pancreatic cancer cells under reduced serum conditions." (PMID 21880146, 2011).
pancreatic cancer (continued). "Previous studies showed that mesothelin (MSLN) plays important roles in survival of pancreatic cancer (PC) cells under anchorage dependent/independent conditions as well as resistance to chemotherapy." (PMID 21880146, 2011). "Here, we aimed at deciphering how MSLN overexpression in pancreatic cancer cells affects sensitivity to TNF-α-induced apoptosis." (PMID 21880146, 2011). "It was reported recently that mesothelin promoted pancreatic cancer cell proliferation and migration and pancreatic cancer progression, but no molecular mechanism was proposed for these effects." (PMID 19128473, 2009). "MSLN-CAR T cell therapy has been investigated in 15 clinical trials for pancreatic cancer." (PMID 40366419, 2025). "Moreover, serum soluble MSLN levels in pancreatic cancer patients are frequently elevated, indicating its potential utility as a biomarker for this malignancy." (PMID 41400642, 2025). "Taken together, these findings suggest that HSV-MSLN effectively delivers MSLN to infected cells, induces the lysis of pancreatic cancer cells, releasing mediators that promote DCs maturation and potentially shift the TME to a more immunogenically active status." (PMID 40366419, 2025). "One such study involves pancreatic cancer patients undergoing a “prime-boost” regimen, starting with a vaccine using recombinant Listeria bacteria expressing the tumor antigen mesothelin, followed by a G-Vax vaccine derived from two allogeneic pancreatic cancer cell lines." (PMID 40382583, 2025). "Therefore, we replace the two viral γ34.5 neurovirulence genes with the human MSLN gene under the control of a CMV promoter to allow for the delivery of MSLN to the pancreatic cancer cell surfaces." (PMID 40366419, 2025). "Notably, core fucosylated MSLN (Cf-MSLN) was found to be reduced in tumor tissues and serum compared to healthy controls, suggesting its potential as a more specific biomarker for pancreatic cancer than total MSLN levels." (PMID 40164585, 2025). "Silencing the expression of mesothelin inhibited growth of pancreatic tumour cells, suggesting it could be used as a potential treatment of PDAC." (PMID 39434498, 2025). "Therefore, we employed multiplex immunofluorescence to label apCAFs and MSLN in Panc02 orthotopic pancreatic tumor samples, and further analyzed the changes in apCAFs following αMSLN treatment." (PMID 39887656, 2025). "Researchers constructed MSLN-targeted CAR-NK cells and reported that MSLN-CAR-NK cells, in combination with a stimulator of interferon genes (STING) agonist, could effectively eliminate MSLN-positive human pancreatic cancer cells in the AsPC-1 cell line." (PMID 40705122, 2025). "Moreover, the co-expression of MSLN and MUC16 was associated with higher histologic grade, vascular invasion and tumor recurrence rates in pancreatic cancer and portended poorer recurrence-free survival and overall survival in affected patients." (PMID 41400642, 2025). "A tissue microarray survival analysis demonstrated that MSLN expression could predict the likelihood of short-term, cancer-related death after surgery in patients with pancreatic cancer." (PMID 41400642, 2025). "However, clinical trials investigating mesothelin-directed CAR T cells to treat pancreatic cancer have had limited clinical efficacy thus far42 or are currently ongoing (ClinicalTrials.gov: NCT03323944 and NCT04577326)." (PMID 39346763, 2024). "We investigated potential effects of MSLN on chemoresistance and various biological processes in pancreatic cancer cells such as proliferation, metastasis, EMT and cancer stem cell traits so as to provide a new idea for chemotherapy and targeted therapy of pancreatic cancer." (PMID 38628720, 2024). "MSLN had a promotive effect on tumor growth of pancreatic cancer." (PMID 38628720, 2024). "MSLN expression levels varied significantly among different pancreatic cancer cell lines." (PMID 38628720, 2024).
pancreatic cancer (continued). "The unique structural features of Muc16 and mesothelin proteins represent critical biology that may contribute to the success or failure of existing CAR T therapies targeting these antigens in pancreatic cancer." (PMID 39346763, 2024). "EMT was characterized by enhanced migration and invasion, so we speculated that MSLN could promote EMT process in pancreatic cancer." (PMID 38628720, 2024). "The epitopes of MSLN peptides, specifically tailored for cytotoxic T lymphocytes (CTLs) clones, shared sequences previously demonstrated to exert an anti-tumor effect against MSLN-expressing malignant pleural mesothelioma and pancreatic cancer cells." (PMID 39294656, 2024). "Therefore, we believe that MSLN promotes chemoresistance of pancreatic cancer by regulating EMT and tumor cell stemness." (PMID 38628720, 2024). "Mesothelin is widely recognized as a marker of aggressiveness in lung and pancreatic cancers." (PMID 38396817, 2024). "We hypothesize that MSLN plays a role in chemoresistance and is associated with intercellular-matrix adhesion, proliferation, invasion, metastasis and EMT of pancreatic cancer cells." (PMID 38628720, 2024). "We will explore other biological functions of MSLN in pancreatic cancer in future studies." (PMID 38628720, 2024). "While mesothelin is robustly expressed in pancreatic cancers, one additional theory is that targeting the glycosylated portion is susceptible to cleavage, which could offer a mechanism that limits CAR T cell efficacy." (PMID 39346763, 2024). "The expression level of MSLN varied greatly in different pancreatic cancer cell lines." (PMID 38628720, 2024). "It is unclear if MSLN is related to chemotherapy resistance of pancreatic cancer." (PMID 38628720, 2024). "According to our previous study, pancreatic cancer highly expressed MSLN." (PMID 38628720, 2024). "MSLN could promote intercellular-matrix adhesion, proliferation, migration and invasion of pancreatic cancer cells, which might lead to distant metastasis." (PMID 38628720, 2024). "Mesothelin is expressed in > 90% of pancreatic cancers, making it an attractive target for therapy." (PMID 37880707, 2023). "Mesothelin (MSLN) is a cell-surface glycoprotein with limited expression on normal tissue but is overexpressed in many solid cancers, including ovarian, lung, and pancreatic carcinomas, making MSLN a promising target for cancer therapies, including CAR-engineered cell therapies." (PMID 37938576, 2023). "The solid tumors involved in these articles mainly include glioblastoma (related targets: IL13Rα2, EGFRvIII, and HER2), neuroblastoma (related target: GD2), sarcoma (related target: HER2), and pancreatic cancer (related target: mesothelin), especially glioblastoma." (PMID 35371087, 2022). "Emerging topics in this field mainly included the study of CAR-T cells in glioblastoma (related targets: IL13Rα2, EGFRvIII, and HER2), neuroblastoma (related target: GD2), sarcoma (related target: HER2), and pancreatic cancer (related target: mesothelin), especially glioblastoma." (PMID 35371087, 2022). "Emerging topics in this field mainly include the study of CAR-T cells in glioblastoma (related targets: IL13Rα2, EGFRvIII, and HER2), neuroblastoma (related target: GD2), sarcoma (related target: HER2), and pancreatic cancer (related target: mesothelin), especially glioblastoma." (PMID 35371087, 2022). "The same team validated the use of anti-mesothelin IL-7/CCL19-producing human CAR-T cells in a preclinical model of orthotopic pre-established malignant mesothelioma, as well as in patient derived xenograft (PTX) models of mesothelin-positive pancreatic cancer." (PMID 35211124, 2022). "The core fucosylated-MSLN levels in pancreatic cancer tissues could scarcely became a routinely used biomarker, due to the invasiveness of the sample obtention." (PMID 36009489, 2022).
pancreatic cancer (continued). "Anetumab ravtansine, an ADC of anti-MSLN antibody linked to maytansinoid DM4 drug, was tested in a phase I study in metastatic solid tumours, including pancreatic cancer (NCT01439152)." (PMID 35892707, 2022). "At present, MSLN is widely studied in pancreatic cancer, colorectal cancer, and other solid tumors." (PMID 35692779, 2022). "Indeed, amatuximab, a chimeric monoclonal anti-MSLN antibody, showed an enhanced anti-tumor effect of gemcitabine against mesothelin, highly expressing pancreatic cancer cell metastasis in a mouse model." (PMID 35883451, 2022). "As the expression of mesothelin on normal cells is limited, targeting of this antigen may prove promising as a treatment in pancreatic cancer." (PMID 33546207, 2021). "In pancreatic cancer, the disruption of YAP transcriptional activity by Super-TDU suppresses secreted YAP/TEAD target genes implicated in extracellular matrix remodeling, such as AREG, CTGF, CYR61, fibroblast growth factor 1 (FGF1) and mesothelin (MSLN)." (PMID 33467099, 2021). "Similarly, treatment with mAbs targeting podocalyxin, HER2, glypican-1, cell surface plectin 1, galectin-9, RON, BAG3, CLDN18.2, mesothelin, vimentin and doublecortin-like kinase 1 inhibited the growth of pancreatic tumours in xenograft models." (PMID 33917882, 2021). "In addition, mesothelin blockage suppressed the adhesion of pancreatic cancer cells to mesothelium in a peritoneal dissemination mouse model." (PMID 33637083, 2021). "The main targets of CAR-T therapy for solid tumors include ganglioside GD2 in neuroblastoma, mesothelin in pancreatic cancer, carcinoembryonic antigen in CRC, fibroblast activation protein in malignant pleural mesothelioma, and epidermal growth factor receptor in non-small cell lung cancer." (PMID 34659553, 2021). "Among these strategies, the feasibility of combinatorial antigen recognition approach has been confirmed in the different solid tumors, including HER2+MUC1+ breast cancer, PSCA+PSMA+ prostate cancer, GPC3+ASGR1+ hepatocellular carcinoma and CEA+MSLN+ pancreatic cancer." (PMID 33292688, 2020). "Mesothelin (MSLN) is a glycoprotein present mainly in mesothelial cells and overexpressed in a variety of human cancers including malignant pleural mesothelioma, ovarian, lung and pancreatic cancers." (PMID 30809507, 2019). "A clinical trial in its recruitment phase for investigating the safety, efficacy and tolerability of anti-mesothelin antibody (BMS-986148) in conjunction with anti-PD-1 (nivolumab) in patients with advanced solid tumors including patients with pancreatic cancer (NCT02341625) is underway." (PMID 29854291, 2018). "Mesothelin tumor vaccines are currently being evaluated, and their safety was established in a phase I clinical trial of patients with mesothelin-expressing advanced cancers, including pancreatic cancer." (PMID 30140382, 2018). "Here, we demonstrated that the anti-mesothelin antibody amatuximab suppressed peritoneal metastases and enhanced the anti-tumor effects of gemcitabine in peritoneal metastases of AsPC-1-Gluc cells in a mouse model of pancreatic cancer." (PMID 30333914, 2018). "Our results suggest that blockade of mesothelin by amatuximab may be a useful strategy for preventing the peritoneal dissemination of pancreatic cancer under an adjuvant setting." (PMID 30333914, 2018). "In addition, CD4+ T-cell mesothelin epitopes were also shown to induce IFN-γ production in peripheral blood from patients with pancreatic cancer." (PMID 29854291, 2018). "Furthermore, high expression of mesothelin was correlated with poor prognosis in several human cancers, and in pancreatic cancer, the coexpression of MUC16 and mesothelin was reported to be an independent prognostic factor for poor prognosis." (PMID 30140382, 2018).
pancreatic cancer (continued). "Mesothelin-specific T cell responses have been observed in peripheral blood lymphocytes from patients with pancreatic cancer, including individuals who were administered a cancer vaccine candidate overexpressing mesothelin peptides and granulocyte-macrophage colony-stimulating factor." (PMID 29854291, 2018). "However, mesothelin is overexpressed in a high percentage of ovarian cancers, pancreatic cancers, non–small lung cancers, and mesotheliomas, making it a potential target for anti-cancer treatments." (PMID 29474384, 2018). "Such immunotoxins, targeting mesothelin on pancreatic cancer cells or the transferrin receptor on small cell lung cancer cells, were successfully combined with ABT-263/737 and induced death in cells that were shown to be resistant against the individual components." (PMID 28868037, 2017). "Two recent reports have shown that MSLN promotes pancreatic cancer cell motility and invasion, while others have demonstrated that it may play an important role in cell adherence, cell survival and proliferation, tumor progression and chemoresistance." (PMID 28632775, 2017). "An in vivo enhancement of mesothelin-targeting rITs by paclitaxel has been described in xenograft models of solid tumors including the mesothelin-expressing pancreatic cancer cell line KLM-1, breast cancer cell line HCC-70, gastric cancer cell line MKN-28, and the cervical cancer cell line KB." (PMID 28423727, 2017). "As the distribution of 64Cu-DOTA-11-25 mAb in the pancreas or stomach was of very low level, MSLN-positive pancreatic cancer or gastric cancer could be visualized in high contrast by in vivo PET imaging with 64Cu-DOTA-11-25 mAb." (PMID 25883990, 2015). "Moreover, biocomputational tools allowed to demonstrate that among the most differentially expressed genes in pancreatic cancer were Mesothelin, Muc4, Muc5A/C, Kallikrein 10, Transglutaminase 2, Fascin, TMPRSS3 and Stratifin." (PMID 25275504, 2014). "However, in mouse models of pancreatic cancer, MSLN overexpression was shown to promote metastasis and proliferation of tumour cells." (PMID 24520352, 2014). "Therefore, N-ERC/mesothelin can be used for quantitative analysis of the therapeutic effect of anti-cancer agents on pancreas cancer in the animal models used in this study." (PMID 25347530, 2014). "Evidence from other studies have shown that detectable T cell responses against MSLN are present in pancreatic cancer patients, suggesting that MSLN over-expression may stimulate clinically meaningful self-restricted T cell responses." (PMID 24520352, 2014). "For that sake, short term T cell lines were generated from PBMCs of 16 healthy controls, 15 patients with benign pancreatic diseases and 25 patients with pancreatic carcinoma and Mesothelin-specific CD4+ and CD8+ T cell responses were analysed using intracellular cytokine assays for IFN-γ." (PMID 24520352, 2014). "A mesothelin tumor vaccine (CRS-207) is currently in a phase II trial in combination with the pancreatic cancer vaccine GVAX, and a pre-clinical in vitro study has reported the success of a lentivirus-expressing anti-mesothelin microRNA (MSLNmiR3) that silences the mesothelin gene (MSLN)." (PMID 24024776, 2013). "Mesothelin, a secreted protein, is overexpressed in some cancers, including pancreatic cancer." (PMID 23034174, 2012). "In pancreatic cancer cells, forced expression of mesothelin significantly increased tumor cell proliferation and migration by 90% and 300%, respectively, and increased tumor volume by 4-fold in the nude mice xenograft model when compared with the vector control cell line." (PMID 23034174, 2012). "Interestingly, none of the expression patterns of the known TEAD1 cofactors such as YAP matched the expression of MSLN in pancreatic cancers or in other cell line models used here." (PMID 23029054, 2012).